MMP13 (matrix metallopeptidase 13)
Diseases named in the same sentence as MMP13 in open-access papers (continued):
Sharing a sentence is not in itself a finding about the gene and the disease.
tumor (continued). "Furthermore, FoxO3A activation has been also shown to cause tumor progression through induction of matrix metalloproteinase, such as MMP-9 and MMP-13." (PMID 25704884, 2015). "MMP13 is an interstitial collagenase that is capable of cleaving multiple collagens, preferentially collagen II, as well as other matrix substrates such as gelatin, fibronectin, and aggrecan relevant to tumor metastasis." (PMID 25880591, 2015). "The use of selective MMP13 inhibitors may be an important step to control tumor growth and metastasis to the liver, however in the past, the clinical use of MMP inhibitors has been hampered by their lack of specificity." (PMID 25880591, 2015). "We thus hypothesize that both stromal and tumor derived MMP13 play an important role in modulating the liver microenvironment and facilitate the establishment of liver metastasis." (PMID 25880591, 2015). "We thus speculate that the promotion of invasion and metastasis by MMP-13 occurs through these smaller Ln-5 γ2 fragments, which may facilitate tumor invasion through ECM and promote metastasis." (PMID 25749207, 2015). "Interestingly, apart from affecting the migration of endothelial cells, MMP-13 also promoted tumor angiogenesis through induction of VEGF-A secretion from fibroblasts and endothelial cells." (PMID 24531055, 2014). "This implies that significance of using MMP13 as a prognostic marker may be more pronounced after taking into account the patient's lymph node status and tumor stage." (PMID 25401159, 2014). "In this study, we defined the malignancy status (angiogenesis, TGF-β1 expression, MMP13 expression, tumor recurrence and lung metastasis) and poor-prognosis indicators (decreased BWG and increased TV and TW) that are associated with increased cell stiffness and adhesion force." (PMID 24581230, 2014). "However, only MMP-13 knockdown blocks dissemination of Pit-1-overexpressing tumor cells to lung, suggesting that MMP-13 mediates in this process." (PMID 25527274, 2014). "In this study, we also observed the colocalization of CD31 and MMP13 in the tumor tissues." (PMID 24581230, 2014). "Interestingly, re-expression of Foxm1 in SPDEF-deficient tumor cells restored cell migration, coinciding with elevated levels of MMP2, MMP9 and MMP13." (PMID 25254494, 2014). "In order to explore whether knockdown of each of these MMPs could also modify the metastatic potential of Pit-1-overexpressing MCF-7 cells in vivo, we evaluated the effect of MMP-1 and MMP-13 knockdown in an SCID mice tumor xenograft model." (PMID 25527274, 2014). "In our study, both MMP-1 and MMP-13 expression was observed in all three cell types studied (tumor cells, fibroblasts, and MICs), but we only found a significant correlation between MMP-1 and MMP-13 positive expression and high Pit-1 levels in tumor cells and fibroblasts." (PMID 25527274, 2014). "However, despite this increase in Collagen I content at the tumor boundaries in the MMP13 KO mice, overall collagen ordering at tumor boundaries was decreased (i.e. more random) in these MMP13 KO mice versus WT controls." (PMID 24010522, 2013). "In addition, whole tumour MMP13 protein amount, analysed from tumour lysates and reflecting tumour and stromal cells, as well as ECM content, was not correlated with nodal status." (PMID 24229053, 2013). "In particular, a recent finding demonstrates MMP13 as a key regulator in osteolytic bone metastasis, where its expression may be induced in osteoblats by tumor-cell derived factors such as oncostatin M and the acute response apolipoprotein SAA3." (PMID 22253746, 2012). "Indeed, we detected MMP13 expression in the tumor and osteoblasts cells in the bone metastases samples, whereas osteoclasts were largely negative for MMP13." (PMID 22253746, 2012).
tumor (continued). "The MMP-13 silencing persisted also following in vivo inoculation, and resulted not only in a diminished bone erosion in the presence of tumour masses of similar size but also in a significant reduction of TRAP positive cells in bone marrow and within the tumour masses." (PMID 22032644, 2011). "We thus hypothesized that MMP-13 might be involved in the complex network of interactions between tumour and bone cells promoting not only OC bone-destructive activity, but also OC differentiation." (PMID 22032644, 2011). "While this finding suggests that MMP-13 is likely to play a role in promoting tumor invasion and metastasis, future studies are needed to clarify whether the MMP-13 protein was expressed by both cancer cells and fibroblasts or by tumor cells alone." (PMID 18373849, 2008). "The Mmp13 mRNA signal was seen in stromal fibroblast-like cells located in the tumor core in areas with invasive grade II and III carcinoma (“late carcinoma”), but was generally absent in the tumor periphery that was dominated by normal-looking mammary tissue, hyperplasia or MIN grade I and II." (PMID 18698413, 2008). "It is also noteworthy that the expression of MMP-13 may be related to tumor biological aggressiveness and used to aid in predicting patient's poor prognosis." (PMID 18554405, 2008). "The correlation of MMP-13 with poor OS and tumor infiltration of lymph nodes suggests that it may promote tumor invasion." (PMID 18373849, 2008). "Mmp13 mRNA expressing myofibroblasts are often found in the tumor core close to areas with necrosis suggesting that MMP13 may be upregulated in response to hypoxia for stimulation of angiogenesis." (PMID 18698413, 2008). "Interestingly, others have reported that MMP-13 protein was restricted to small stromal foci within the tumor masses and was specifically produced by invading tumor cells." (PMID 18373849, 2008). "3- It may become a therapeutic target for jaws chondrosarcoma's patients with MMP-13 positive tumor." (PMID 18554405, 2008). "Furthermore, high levels of MMP-13 in cancer/peritumoral fibroblast cells correlated with tumor infiltration of lymph nodes." (PMID 18373849, 2008). "However, MMP-13 was the only proteinase in our study to localise to the epithelially derived tumour component." (PMID 16465195, 2006). "Besides overexpression of MMP7, a known β-catenin-dependent target gene in colon cancer, the results show an overexpression of MMP1, MMP3, MMP11, MMP12 and MMP13 in desmoid tumours compared to normal fibroblasts (fascia tissue)." (PMID 15054469, 2004). "Notably, HTRA1 from remote tumor-released sEVs was delivered to OPs in the bone marrow, and promoted the upregulation of matrix metalloproteinase 13 (MMP-13) in OPs, thus leading to the dislocation of hematopoietic stem cells and aggregation of CD41− granulocyte-monocyte progenitors (GMPs)." (PMID 40103824, 2025). "Similarly, in colorectal cancer MMP-13 plays an important role in tumor progression." (PMID 41471689, 2025). "Furthermore, the mechanical stretching TGF-β signalling pathway in normal myoepithelial cells induces a DCIS phenotype associated with integrin-β6 expression, thereby affecting the expression of proteases such as MMP13 and promoting the invasion behaviour of tumour cells." (PMID 40243781, 2025). "Notably, MMP13 may be involved in both T cell response and tumor invasion via PD-L1 cleavage and degradation of collagen fibers." (PMID 38774209, 2024). "We further investigated whether MMP13 levels might affect the migration of tumor cells in the TME." (PMID 38774209, 2024). "Therefore, tumor-derived EVs may act as messengers that mediate the interaction between normoxic and hypoxic cancer cells by delivering MMP13 and remodeling the TME of HNSCC." (PMID 37292204, 2023).
tumor (continued). "In addition, endothelial cells oversecrete MMP-13, which could reduce tumor cell extravasation to suppress tumor metastasis through the local generation of endostatin." (PMID 37609436, 2023). "Moreover, even higher MMP-13 expression is seen in the stromal cells surrounding the tumour." (PMID 35805035, 2022). "Moreover, collagenase-3 (MMP-13) can act as an important mediator of tumor cell metastasis." (PMID 36291773, 2022). "Functional studies using crudely isolated and minimally characterized EPs hinted that MMP13+ EPs from the plasma of patients with NPC may mediate the tumor microenvironment by facilitating tumor cell migration and invasion via promoting interaction with stromal cells." (PMID 33158181, 2020). "However, a 3–4-day measurement of tumor size over the course of 10 more days (until animals were killed) indicated that MMP13 expression was required for optimal tumor growth because MMP13-shRNA-expressing ETV4 cells are, on average, twofold smaller than controls." (PMID 29996935, 2018). "This subfamily covers collagenase 1 (MMP-1), collagenase 3 (MMP-13), and the MT-MMPs, membrane-bound MMPs to function not only for extracellular matrix remodeling during organ development and tissue regeneration but also in many pathological situations and tumor progression and metastasis." (PMID 28672814, 2017). "Additionally, by using RNA sequencing, we show that the genes involved in the extracellular matrix remodeling such as MMP13 may contribute to the tumor shape heterogeneity." (PMID 26669540, 2015). "However, we suppose that the process VM disruption by MMP-13 may also facilitate tumor metastasis further." (PMID 25749207, 2015). "However, the tumor burden, incidence and area of liver metastases was markedly reduced in the Mmp13−/− mice compared to the wildtype mice after tumor cell injection, thus supporting the role of MMP13 in metastatic tumor growth to the liver both in normal and steatotic mice." (PMID 25880591, 2015). "In BCa, it was demonstrated that MMP13 was expressed little in normal bladder cells yet it was expressed in tumor cells, particularly at the invading edges, suggesting that MMP13 may serve as a marker for tumor transformation and invasion and can be a potential therapeutic target." (PMID 26517808, 2015). "Moreover, high expression of MMP-13 has been correlated to tumor behavior and prognosis." (PMID 24531055, 2014). "MMP13 helps regulate collagen structure and has been ascribed largely harmful roles in cancer, but some studies demonstrate that MMP13 may also protect against tumor pathology." (PMID 24010522, 2013). "Moreover, there remains limited understanding of exactly how MMP-13 interactions with collagen impact tumor pathology – for example, what structural changes result from these interactions, and how do these changes promote or protect against tumor pathology?" (PMID 24010522, 2013). "Thus, the MMP13 polymorphism does not seem to contribute to initial stages of tumor development, although this evidence needs to be confirmed in further studies." (PMID 19094243, 2008). "To determine whether any effects of MMP13 could be seen on its major substrate, fibrillar collagen, we evaluated the fibrillar collagen content in invasive areas of the tumors by picrosirius red staining of tumor sections." (PMID 18698413, 2008). "During the invasion phase of the primary tumor, TAMs secrete matrix metalloproteinases (MMPs) (e.g., MMP-2, MMP-9, and MMP-13) to degrade the basement membrane and thus establish a pathway for cancer cell invasion." (PMID 41362730, 2026). "In cSCC, the most expressed MMPs by tumor cells and stromal cells are MMP-1, MMP-7, MMP-9, MMP-13, and MMP-14." (PMID 40868818, 2025). "According with these results, one of the most downregulated genes corresponded to matrix metalloproteinase (MMP)-13 (MMP13), highly expressed in invasive stem-like GBM cells and plays an important role in tumor aggressive process by degrading ECM." (PMID 40813676, 2025).
tumor (continued). "Proteolytic cleavage by MMPs, such as MMP-13 and ADAM family proteases, also contributes to sPD-L1 release, with tumor-specific patterns of MMP expression influencing sPD-L1 levels." (PMID 40002913, 2025). "Calcitriol inhibited key tumor progression processes, such as cell proliferation and migration, and downregulated MMP7 and MMP13 mRNAs." (PMID 40168262, 2025). "Here we identified that MMP9, MMP13, VCAM1, and PTX3 overexpression not only promotes ECM remodelling and angiogenesis but also facilitates tumour infiltration, thereby reconfiguring the TME to favour migration and metastasis." (PMID 41007296, 2025). "MMP13 cleaves multiple collagens as well as other extracellular matrix (ECM) substrates such as gelatin, fibronectin, and aggrecan relevant to tumor metastasis." (PMID 40839695, 2025). "Tumor cells promote invasion by upregulating matrix metalloproteinases (MMPs), including MMP7 and MMP13." (PMID 40168262, 2025). "FOXOs contribute to the maintenance of tumor stem cells, mediate drug resistance through the upregulation of the MDR1 protein, and enhance tumor invasiveness by increasing the expression of matrix metalloproteinases (MMP-9 and MMP-13)." (PMID 40424719, 2025). "Conversely, we identified that tumours with low ratios enrich inflammatory/ECM-disrupting genes, such as IL6R, VCAM1, and MMP13, which collectively drive immune suppression and metastasis, in accordance with a poor prognosis and increased invasiveness." (PMID 41007296, 2025). "MM cells are characterized by matrix metalloproteinase 13 (MMP13) secretion, which upregulates glycine levels in the bone marrow and supports tumor growth through pathways including glutathione and purine synthesis." (PMID 41294841, 2025). "The activation of TLR9 in GBM seems to promote hypoxia-induced tumour cell invasion, probably due to the CpG-ODN effect and the activation of MMP-2, MMP-9 and collagenase 3 (MMP-13), as shown in U373 and U87 cell lines." (PMID 38247816, 2024). "Since bsPD-L1+ patients had higher levels of the collagenase MMP13 than bsPD-L1− patients, we evaluated ECM integrity in tumor tissues by EMG staining." (PMID 38774209, 2024). "A recent study suggests that MC-LR activate the PI3K/AKT pathway, which leads to increased matrix metalloproteinase-13 (MMP-13) expression, resulting in enhanced migration and invasion of Duke's Lymphoma Disease 1 (DLD-1) and Human Tumor 29 (HT-29) cells." (PMID 39606777, 2024). "We further distinguished between tumour cells and non‐malignant epithelial cells using several marker genes, including MMP7, MMP9, MMP13 and HOXB2." (PMID 36588094, 2023). "Secondly, F. nucleatum induces activation of protein kinase p38 in infected cells, promoting the secretion of matrix metalloproteinase-13 (MMP-13) and MMP-9, which contributes to tumor invasiveness." (PMID 36407281, 2023). "MMP-10 is expressed by tumor cells in cSCC and it has been shown to contribute to cSCC progression by activating latent MMP-1 and MMP-13." (PMID 37864034, 2023). "Rebimastat, an inhibitor of MMP-1, MMP-2, MMP-3, MMP-8, MMP-9, MMP-13, and MMP-14, significantly abolishes tumor growth and abrogates BC metastasis." (PMID 36993955, 2023). "Previously, it has been documented that MMP-1 and MMP-13 expression is enhanced by TGF-β-activated p38 MAPK pathway in head and neck SCC, promoting collagenolytic and invasive capacity of the tumor cells." (PMID 37864034, 2023). "This increase in MMP13 expression levels was found to be HIF-1α-dependent and induced EMT of the recipient normoxic cell, leading to tumor invasion." (PMID 37292204, 2023). "A study revealed that RA effectively inhibits the expression of matrix metalloproteinase-13 (MMP-13) mRNA, which is known to promote tumor invasion and metastasis by enhancing extracellular matrix degradation during tumor growth." (PMID 37711628, 2023).
tumor (continued). "The expression of SNHG12 is positively correlated with the expression of MMP13, thus, MMP13 induced degradation of extracellular matrix in TNBC cells promotes tumor invasion and metastasis." (PMID 37795578, 2023). "RUNX2 knockdown also led to the decreased levels of RUNX2, MMP13 and MGAT5 in mice tumor tissues when assessed by western blotting or IHC assay." (PMID 37256183, 2023). "MMP-13 expression in stromal fibroblasts was shown to enhance VEGF and VEGFR-2 concentrations in the tumour cell invasive areas around blood vessels and promote angiogenesis in skin carcinoma." (PMID 35805035, 2022). "The protein family of matrix metalloproteinases can degrade extracellular matrix components, whose well-known role is modulating tumor metastases, such as MMP2, MMP9, MMP7, MMP13, and MMP14." (PMID 35690612, 2022). "Additional hub genes MMP13, SFRP4, ADAMTS16 and FNDC1 also significantly affect survival with their expression across tumour grades comparable to CTHRC1." (PMID 36190948, 2022). "MMP-13 and MMP-1 also played a significant role in tumor progression of eyelid BCC in a clinical study, as immunoreaction positivity was identified in most patients." (PMID 35572966, 2022). "IHC confirmed the expression of MMP13 or collagenase 3, which is involved in degradation of the ECM and has been related to tumor angiogenesis." (PMID 35205840, 2022). "In BCC's stroma and the peritumoral area, CAFs can secrete an array of MMPs (e.g., MMP-1, MMP-2, MMP-3, MMP-9, MMP-11, MMP-13, MMP-14, MMP-19), all of them promoting ECM remodeling and favoring tumor escape from the anti-tumoral action of the immune cells." (PMID 35572966, 2022). "MMP-13 is an important enzyme with a role in the digestion of collagen and other components of the ECM, thus facilitating tumor invasion." (PMID 36547091, 2022). "It is involved in tumor invasion and progression and can activate other MMPs, such as MMP-1, MMP-7, MMP-8, MMP-9 and MMP-13, which have an established role in OSCC." (PMID 36547091, 2022). "ECM degradation by MMPs such as MMP-13 releases sequestered growth factors, such as fibroblast growth factors (FGF) and TGF, which aid tumour cell proliferation." (PMID 35805035, 2022). "First, SIS3 inhibited the promotion of the expression of MMP2, MMP13 and VEGF induced by GluOC in tumor cells." (PMID 35413833, 2022). "In SKCM cells, ENO1 overexpression promoted invasion, migration, and proliferation of tumor cells; increased pyruvate and lactate production; and increased β-catenin, MMP-9, MMP-13, and c-Myc levels." (PMID 35925486, 2022). "Aside from these direct effects on angiogenesis, CAFs have also been shown in numerous studies to indirectly affect tumor growth from the ECM through expression of MMPs such as MMP9 and MMP13." (PMID 33808627, 2021). "Tumor cells mitigate the immune response by releasing MMP-2, MMP-9, MMP-13 and MMP-14, resulting in the inhibition of T-cell proliferation and antigen presentation." (PMID 34204372, 2021). "MMP-14 also contributes to the degradation of the extracellular matrix by activating other MMPs, such as pro-MMP-13 and pro-MMP-2, and plays a crucial role in molecular carcinogenesis and tumor growth." (PMID 33946534, 2021). "We evaluated cytoplasmic expression of MMP-13 based on staining index using immunohistochemistry (IHC) in epithelial cells, stromal fibroblasts of IDC (n=90) and benign epithelial breast (n=90) lesions." (PMID 34452576, 2021). "Parallel in other cell type support a potential tumor suppressor role of ZNF750, the present study testified that ZNF750 attenuated cell invasion, migration and MMP13 positive population." (PMID 35003347, 2021). "Matrix metalloproteinase 13 (MMP-13) in NPC-related exosomes upregulates vimentin and reduces cadherin to facilitate tumor invasion, metastasis and angiogenesis; on the other hand, MMP13 expression is trans-activated by hypoxia-inducible factor α (HIF1α) 6,52." (PMID 34239345, 2021).